ENSG00000274409
Gene: Miscellaneous RNA gene on chromosome 7 (96,965,302 to 96,965,481, forward strand). Ensembl gene ENSG00000274409.
Gene Ontology:
Biological process: forebrain development; positive regulation of DNA-templated transcription